DAB2IP (DAB2 interacting protein)
Description:
Functions as a scaffold protein implicated in the regulation of a large spectrum of both general and specialized signaling pathways. Involved in several processes such as innate immune response, inflammation and cell growth inhibition, apoptosis, cell survival, angiogenesis, cell migration and maturation. Also plays a role in cell cycle checkpoint control; reduces G1 phase cyclin levels resulting in G0/G1 cell cycle arrest. Mediates signal transduction by receptor-mediated inflammatory signals, such as the tumor necrosis factor (TNF), interferon (IFN) or lipopolysaccharide (LPS). Modulates the balance between phosphatidylinositol 3-kinase (PI3K)-AKT-mediated cell survival and apoptosis stimulated kinase (MAP3K5)-JNK signaling pathways; sequesters both AKT1 and MAP3K5 and counterbalances the activity of each kinase by modulating their phosphorylation status in response to pro-inflammatory stimuli. Acts as a regulator of the endoplasmic reticulum (ER) unfolded protein response (UPR) pathway; specifically involved in transduction of the ER stress-response to the JNK cascade through ERN1. Mediates TNF-induced apoptosis activation by facilitating dissociation of inhibitor 14-3-3 from MAP3K5; recruits the PP2A phosphatase complex which dephosphorylates MAP3K5 on 'Ser-966', leading to the dissociation of 13-3-3 proteins and activation of the MAP3K5-JNK signaling pathway in endothelial cells. Also mediates TNF/TRAF2-induced MAP3K5-JNK activation, while it inhibits CHUK-NF-kappa-B signaling. Acts a negative regulator in the IFN-gamma-mediated JAK-STAT signaling cascade by inhibiting smooth muscle cell (VSMCs) proliferation and intimal expansion, and thus, prevents graft arteriosclerosis (GA). Acts as a GTPase-activating protein (GAP) for the ADP ribosylation factor 6 (ARF6), Ras and RAB40C. Promotes hydrolysis of the ARF6-bound GTP and thus, negatively regulates phosphatidylinositol 4,5-bisphosphate (PIP2)-dependent TLR4-TIRAP-MyD88 and NF-kappa-B signaling pathways in endothelial cells in response to lipopolysaccharides (LPS). Binds specifically to phosphatidylinositol 4-phosphate (PtdIns4P) and phosphatidylinositol 3-phosphate (PtdIns3P). In response to vascular endothelial growth factor (VEGFA), acts as a negative regulator of the VEGFR2-PI3K-mediated angiogenic signaling pathway by inhibiting endothelial cell migration and tube formation. In the developing brain, promotes both the transition from the multipolar to the bipolar stage and the radial migration of cortical neurons from the ventricular zone toward the superficial layer of the neocortex in a glial-dependent locomotion process. Probable downstream effector of the Reelin signaling pathway; promotes Purkinje cell (PC) dendrites development and formation of cerebellar synapses. Also functions as a tumor suppressor protein in prostate cancer progression; prevents cell proliferation and epithelial-to-mesenchymal transition (EMT) through activation of the glycogen synthase kinase-3 beta (GSK3B)-induced beta-catenin and inhibition of PI3K-AKT and Ras-MAPK survival downstream signaling cascades, respectively.
Synonyms: AIP-1; AF9Q34; AIP1; KIAA1743; DIP1/2
Tractability: Small molecule: a high-quality ligand is known. Antibody: UniProt places it where antibodies can reach, with high confidence; its Gene Ontology location is reachable by antibodies, with high confidence. PROTAC: ubiquitination databases record sites on it; its protein half-life has been measured; a small molecule that binds it is known.
Gene: Protein-coding gene on chromosome 9 (121,567,057 to 121,785,530, forward strand). Ensembl gene ENSG00000136848.
Subcellular location: Cytoplasm; Cell membrane; Membrane; Cell projection, dendrite
Pathways (Reactome):
Signal Transduction: Regulation of RAS by GAPs
Gene Ontology:
Molecular function: 14-3-3 protein binding; cadherin binding; death receptor binding; GTPase activator activity; identical protein binding; kinase binding; mitogen-activated protein kinase kinase binding; mitogen-activated protein kinase kinase kinase binding; phosphatidylinositol 3-kinase binding; phosphatidylinositol 3-kinase regulatory subunit binding; phosphatidylinositol-3-phosphate binding; phosphatidylinositol-4-phosphate binding; protein binding; protein homodimerization activity; protein kinase binding; protein phosphatase 2A binding; protein serine/threonine kinase activator activity; protein-containing complex binding; SH3 domain binding; signaling adaptor activity; Toll-like receptor 4 binding; vascular endothelial growth factor receptor 2 binding
Biological process: cellular response to interleukin-1; cellular response to lipopolysaccharide; cellular response to tumor necrosis factor; cellular response to vascular endothelial growth factor stimulus; extrinsic apoptotic signaling pathway via death domain receptors; intracellular signal transduction; lipid droplet formation; negative regulation of angiogenesis; negative regulation of canonical NF-kappaB signal transduction; negative regulation of canonical Wnt signaling pathway; negative regulation of cell population proliferation; negative regulation of DNA-templated transcription; negative regulation of endothelial cell migration; negative regulation of epithelial cell migration; negative regulation of epithelial cell proliferation; negative regulation of epithelial to mesenchymal transition; negative regulation of ERK1 and ERK2 cascade; negative regulation of G0 to G1 transition; negative regulation of MAPK cascade; negative regulation of non-canonical NF-kappaB signal transduction; negative regulation of phosphatidylinositol 3-kinase/protein kinase B signal transduction; negative regulation of protein catabolic process; negative regulation of Ras protein signal transduction; negative regulation of toll-like receptor 4 signaling pathway; negative regulation of transcription by RNA polymerase II; and 36 more
Cellular component: AIP1-IRE1 complex; cytoplasm; endocytic vesicle; membrane; plasma membrane; axon; cerebellar mossy fiber; climbing fiber; cytosol; neuronal cell body; neuronal cell body membrane; parallel fiber; dendrite
Genetic constraint (gnomAD): Loss-of-function variants: 28 observed, 94.39 expected, observed/expected ratio (o/e) 0.3, 90% interval 0.22 to 0.41. The upper end of that interval is the gene's LOEUF score, 0.41, which puts it in group 1 of 6, group 1 being the genes least tolerant of losing a copy. Missense variants: 1,400 observed, 1,565 expected, observed/expected ratio (o/e) 0.89, 90% interval 0.86 to 0.94. Synonymous variants: 755 observed, 658.95 expected, observed/expected ratio (o/e) 1.15, 90% interval 1.08 to 1.22.
Homologues: Orthologues: chimpanzee DAB2IP (100% identical), guinea pig DAB2IP (98% identical), pig DAB2IP (98% identical), rat Dab2ip (98% identical), mouse Dab2ip (97% identical), rabbit DAB2IP (97% identical), macaque DAB2IP (82% identical), tropical clawed frog dab2ip (79% identical), zebrafish dab2ipb (74% identical), zebrafish dab2ipa (73% identical), Caenorhabditis elegans gap-2 (29% identical), Drosophila melanogaster raskol (18% identical). Paralogues in human: RASAL2 (57% identical), RASAL3 (28% identical), RASAL1 (15% identical), RASA3 (15% identical), RASA4 (15% identical), RASA4B (15% identical), NF1 (14% identical), RASA2 (13% identical), RASA1 (11% identical).
Diseases named in the same sentence as DAB2IP in open-access papers:
DAB2IP is named in the same sentence as 77 diseases in open-access papers, as found by Europe PMC text mining. Sharing a sentence is not in itself a finding about the gene and the disease. The quoted sentences say what the papers report.
prostate carcinoma (47 papers, 2010 to 2025). A carcinoma that arises from epithelial cells of the prostate gland. "We later confirmed that DAB2IP loss-of-function amplifies NF-κB activation and contributes to a pro-inflammatory gene expression pattern in breast and prostate cancer cells." (PMID 38902547, 2024). "Kong Z and colleagues present evidence suggesting that DAB2IP-deficient prostate cancer cells that have metastasized show greater clonogenic survival when treated with ionizing radiation than control cells expressing normal levels of DAB2IP." (PMID 39132508, 2024). "The researchers eliminated endogenous DAB2IP from a metastatic prostate cancer cell line using the shRNA-lentiviral system and performed Western blot analysis to confirm the loss of DAB2IP protein expression." (PMID 39132508, 2024). "DAB2IP is frequently silenced in advanced prostate cancer (PCa) and is associated with aggressive phenotypes of PCa." (PMID 34775484, 2022). "A GWAS in humans revealed associations of this gene with aggressive prostate cancer, DAB2IP being a candidate tumor suppressor gene." (PMID 33731010, 2021). "Specifically, the DAB2IP gene was found to play a tumor suppressor role in medulloblastoma and a lower expression of DAB2IP caused resistance to radiation in prostate carcinoma." (PMID 30344926, 2018). "A potential tumor-suppressive role of DAB2IP has recently been highlighted in a prostate cancer model, where DAB2IP gene loss activated both RAS and NFκB." (PMID 26299805, 2015). "This study suggests that about one‐fourth of men with high‐risk prostate cancer have decreased tumor expression of DAB2IP." (PMID 26471467, 2015). "Loss of DAB2IP, a novel tumor suppressor gene, is associated with the high risk of aggressive prostate cancer (PCa)." (PMID 26512963, 2015). "For example, loss of DAB2IP, a RasGTPase-activating protein (RasGAP), induced prostate cancer metastasis and its expression is inversely correlated with tumor grade and predicts prognosis." (PMID 25004126, 2014). "Recent studies have identified DAB2IP as a regulator of metastatic prostate cancer, and is one of the few genes with a direct causal role in driving prostate cancer metastasis." (PMID 24912918, 2014). "Treatment with a Ras signaling pathway inhibitor, FTI-277, resulted in radiosensization of DAB2IP deficient PC-3 prostate cancer cells." (PMID 23351141, 2013). "The loss of DAB2IP gene expression in prostate cancer cells produces an efficient DNA double-strand break repair, less cell cycle arrest and the development radiation resistance cells." (PMID 23351141, 2013). "Recently, one study reported that a genetic polymorphism (rs1571801) in intron 1 of DAB2IP gene was significantly associated with increased risk of aggressive prostate cancer both in African American and European population." (PMID 22046421, 2011). "One genetic variant in DAB2IP gene was reported to be associated with an increased risk of aggressive prostate cancer recently." (PMID 22046421, 2011). "Additional specific dependencies may be targetable in these tumors; for instance, since DAB2IP levels show strong inverse correlation with AR activation in CRPC, DAB2IP-deficient prostate cancers may be particularly sensitive to AR inhibitors." (PMID 38902547, 2024). "In a study published in 2010, Kong Z and colleagues presented evidence suggesting that DAB2IP-deficient prostate cancer cells that have metastasized show greater clonogenic survival when treated with ionizing radiation than control cells expressing normal levels by DAB2IP." (PMID 39132508, 2024). "Both PRRT2 and DAB2IP were mutated in three out of the four MSI prostate cancer cell lines." (PMID 27907910, 2017). "In this study, similar to the results from prostate cancer, we also observed that DAB2IP-deficient renal cells acquired CSC potential based on CSC hallmarks such as sphere-forming ability under ultralow-attachment growth condition and increased side population (SP)." (PMID 28978010, 2017).
prostate carcinoma (continued). "Based on the results presented herein, DAB2IP may be able to differentiate the worst cases amongst the already high‐risk group of prostate cancer patients that are at greatest risk for treatment failure prior to initiation of standard therapy." (PMID 26471467, 2015). "In conclusion, based on our results about one‐fourth of men with high‐risk prostate cancer and well over 10,000 men in the United States annually may have reduced tumor expression of DAB2IP which makes their tumors more radioresistant and aggressive." (PMID 26471467, 2015). "Because most of the lung cancer patients are males and DAB2IP deficient was also founded in lung cancer, it is likely that the genetic variation in DAB2IP gene may contribute to increase the risk of lung cancer as it did in prostate cancer." (PMID 22046421, 2011). "However, DAB2IP loss also conferred resistance to prostate cancer through modulation of apoptosis." (PMID 34140969, 2021). "We employed CRISPR/Cas9 gene editing to generate two prostate cancer cell models in which endogenous DAB2IP is fused to HiBiT, a peptide tag that enables luminescence-based detection of protein levels in a sensitive and quantitative manner." (PMID 40867592, 2025). "Due to hypermethylation of the DAB2IP gene promoter, prostate cancer C4-2 cells exhibit down-regulated endogenous DAB2IP expression." (PMID 41261855, 2025). "This study provides evidence that DAB2IP is a potentially druggable molecule and its drug-induced upregulation can counteract various pro-oncogenic features in prostate cancer cell lines." (PMID 40867592, 2025). "In recurrent prostate cancer, the expression of DAB2IP is inversely correlated with androgen receptor activation, and DAB2IP expression in PCa cells can suppress androgen-induced cell proliferation and gene activation." (PMID 38902547, 2024). "In prostate cancer, DAB2IP prevents EMT induced by IFN-γ treatment by dampening the JAK/STAT1 response and preventing upregulation of IFIT5, a gene involved in XRN1-mediated turnover of the anti-metastatic microRNA miR-363." (PMID 38902547, 2024). "Early studies in prostate cancer (PCa) cells showed that DAB2IP overexpression downregulates EMT markers and inhibits tumor growth and metastasis." (PMID 38902547, 2024). "For instance, DAB2IP overexpression restored drug sensitivity in prostate cancer cells, by reducing the levels of the anti-apoptotic factor Clusterin." (PMID 38902547, 2024). "In prostate cancer and glioblastoma multiforme, DAB2IP induced β‐catenin degradation by inhibiting GSK‐3β phosphorylation at S9." (PMID 36536485, 2022). "Downregulating DAB2IP induces radioresistance in prostate cancer (PCa) cells by enhancing the repair of damaged DNA and maintaining a robust G2 cell cycle checkpoint." (PMID 34775484, 2022). "Meanwhile, decreased levels of DAB2IP were also responsible for enhanced CSC phenotypes in prostate cancer through the PI3K/AKT/mTOR pathway." (PMID 30770783, 2019). "The repression of DAB2IP gene controls the conveying apoptosis resistance in immortalized neural precursor and medulloblastoma cells, and in prostate cancer by polycomb EZH2 complex." (PMID 31666665, 2019). "Recently, DAB2IP was identified as a DOC-2/DAB2 interactive protein with the growth-inhibitory effect in prostate cancer." (PMID 29743885, 2018). "Downregulation of DAB2IP induces radioresistance by accelerating DNA double strand repair after radiation and evasion of apoptotic process in prostate carcinoma." (PMID 30344926, 2018). "MiR-32 promotes radioresistance by targeting DAB2IP and regulating autophagy in prostate cancer cells." (PMID 29459645, 2018). "In SIRT7-deficient cells, E-cadherin and DAB2 interacting protein (DAB2IP; a tumor suppressor gene, whose loss promotes EMT and metastasis in prostate cancer) are significantly increased in mRNA level." (PMID 30510540, 2018).
prostate carcinoma (continued). "Previously, we demonstrated the comprehensive inhibitory effect of DAB2IP on various CSC subpopulation in prostate cancer via different mechanism of action." (PMID 28978010, 2017). "The core promoter sequence hypermethylation and histone deacetylation cooperatively silence the DAB2IP gene expression in prostate cancer and other cancer types." (PMID 26658103, 2016). "In prostate cancer, it was identified that downregulation of DAB2IP expression promotes resistance to ionizing radiation, initiates epithelial-to-mesenchymal transition and drives tumor growth and metastasis." (PMID 27036023, 2016). "In prostate cancer, DAB2IP expression was repressed by promoter methylation and histone modification." (PMID 26658103, 2016). "We first shifted emphasis to its role in cancer metastasis and found that the loss of DAB2IP expression initiates EMT in both human normal prostate epithelial and prostate carcinoma cells, as well as in clinical PCa specimens." (PMID 26658103, 2016). "In prostate cancer, DAB2IP functions as a scaffold protein in regulating EMT through GSK3β-β-catenin signaling pathway." (PMID 26336990, 2015). "Based on strong preclinical data indicating the role of DAB2IP in radiation response in prostate cancer cells, we performed a pilot study to determine its clinical importance." (PMID 26471467, 2015). "In prostate cancer, the reciprocal regulation between DAB2IP and Skp2 can impact on the growth of prostate cancer cells." (PMID 26336990, 2015). "This subpopulation with reduced DAB2IP has a suboptimal response and significantly higher prostate cancer‐specific mortality despite standard of care treatment with radiation therapy and androgen deprivation." (PMID 26471467, 2015). "To date, a significant prevalence of DAB2IP lost has been found in several different tumor types, including prostate cancer, hepatocellular cancer, breast cancer and lung cancer." (PMID 26336990, 2015). "Other groups previously reported that DAB2IP suppressed EMT by modulating GSK3β/β-catenin signaling pathway in prostate cancer." (PMID 26336990, 2015). "Mechanistically, DAB2IP is involved in TNFα-induced apoptosis in prostate cancer cells by suppressing the ASK1-JNK and PI3K-Akt pathway, and in endothelial cells via the ASK1-JNK pathway." (PMID 24912918, 2014). "Altered DAB2IP gene expression often detected in prostate cancer (PCa) is due to epigenetic silencing." (PMID 25115390, 2014). "In order to unveil the role of Skp2 in the turnover of DAB2IP protein, both prostate cell lines and prostate cancer specimens with a variety of molecular and cell biologic techniques were employed." (PMID 25115390, 2014). "DAB2IP plays an important role in regulating the cell growth and survival of prostate cancer through its GAP domain in suppressing Ras-Raf-ERK activation or proline-rich (PR) domain in suppressing PI3K-dependent Akt phosphorylation." (PMID 25115390, 2014). "Given a causal role for DAB2IP in driving progression of prostate cancer towards metastasis, and the prevalence of PTEN loss early in prostate cancer development, understanding how DAB2IP is regulated is of critical importance." (PMID 24912918, 2014). "Immunohistochemical study exhibited an inverse correlation between DAB2IP and Skp2 protein expression in the prostate cancer tissue microarray." (PMID 25115390, 2014). "Recent studies have demonstrated that prostate cancer (PCa) cells can acquire radio-resistance when DOC-2/DAB2 interactive protein (DAB2IP) is downregulated." (PMID 25015118, 2014). "Of particular interest is that DAB2IP differentially regulates GSK3β activity in hMSCs and prostate cancer cells; DAB2IP activates GSK3β in prostate cancer cells but represses GSK3β in hMSCs." (PMID 24073285, 2013). "DAB2IP is a member of GTPase-activating protein family inhibiting the Ras- mediated signal pathway and is often downregulated in prostate cancer, i. e., a potential tumor suppressor gene." (PMID 23351141, 2013).